IL5 (interleukin 5)
Diseases named in the same sentence as IL5 in open-access papers (continued):
Sharing a sentence is not in itself a finding about the gene and the disease.
Sepsis (continued). "In addition, IL-33, IL-13, and IL-5 have also been reported to prevent acute lung injury during sepsis." (PMID 34616745, 2021). "In summary, IL-5 can directly slow down the lung injury induced by sepsis." (PMID 34057015, 2021). "Therefore, further exploration of the relationship between IL-5 and immune response can provide a new target for the treatment of sepsis-induced ALI." (PMID 34057015, 2021). "It has been shown that IL-5 in peripheral blood of sepsis patients decreases significantly." (PMID 34057015, 2021). "However, direct evidence linking the IL-5 signaling pathway to sepsis is currently limited." (PMID 41259376, 2025). "In addition, it is known that IL-33 is a potent activator of type 2 Innate Lymphoid Cells (ILC2), which results in enhanced production of the key effector cytokines IL-5 and IL-13, and that IL-33 plays a major role in local inflammatory changes in the lung, early after the onset of sepsis." (PMID 38279209, 2024). "In addition, Xu has shown that the reasons may be that the up-regulation of IL-5 can directly target IL-5 Rα and slow down the recruitment of active neutrophils and monocytes to the lung, thus alleviating sepsis-induced ALI." (PMID 34057015, 2021). "So, we speculate that IL-5 has therapeutic potential for sepsis and its complications." (PMID 34057015, 2021). "Therefore, in the current study, we tested whether the levels (in cord and venous blood) of some of the key cytokines of Th1 (IFN-γ) and Th2 (IL-5) phenotypes, may have predictive role in early diagnosis of sepsis in preterm neonates, along with some standard laboratory analysis." (PMID 33521320, 2021). "In the present study, we evaluated the potential predictive role of IFN-γ and IL-5 in cord and venous blood, together with the determination of C-reactive protein and procalcitonin (PCT) for sepsis development in premature neonates." (PMID 33521320, 2021). "This IL-33 dependent ALI during sepsis also occurs via IL-5 upregulation in pulmonary ILC2s, and the IL-5 neutralization decreases the neutrophil infiltration, and ALI during sepsis." (PMID 32849610, 2020). "To clarify whether AAM were involved in the L. sigmodontis-mediated protection against an E. coli-induced sepsis, we used IL-4Rα/IL-5 double deficient BALB/c mice—which do not develop AAM, and IL-4-deficient BALB/c mice, which lack the suppressive effect of AAM." (PMID 25611587, 2015). "For what we believe is the first time, however, we also demonstrate that levels of eotaxin, IL-5, IL-15, M-CSF, MIG, MIP-1α, MIP-1β, and MIP-2 rise significantly during sepsis." (PMID 24725742, 2014). "The presence of interleukin (IL)‐2, IL‐4, IL‐5, IL‐6, IL‐8, IL‐10, TNF‐α and interferon‐γ was significantly more evident in all three cell culture media transfected with plasma from sepsis patients than in controls, indicating that the transfected cells potentially underwent necroptosis." (PMID 40318009, 2025). "On the other hand, concentration of IL-5 in cord blood and venous plasma did not significantly differ between sepsis groups (P > 0.05) as well as when sepsis and control groups of preterm infants are compared." (PMID 33521320, 2021). "On the other hand, levels of IL-5 did not significantly change in the evaluated groups of sepsis and in the control group of participants." (PMID 33521320, 2021). "Therefore, we investigated blood IL-1β, IL-6, IL-4, IL-5, IL-10 and IFN-γ, which play important roles in sepsis." (PMID 26586517, 2015). "However, because of the complexity of the immune response, the mechanism of how IL-5 alleviates sepsis-induced lung injury by regulating immune response has not yet been well revealed." (PMID 34057015, 2021). "Our study results showed that IL-5 levels did not significantly differ between evaluated groups, as well as we compared IL-5 levels in cord and venous blood, suggesting that IL-5 may not be credible predictor for sepsis development in preterm neonates." (PMID 33521320, 2021).
Sepsis (continued). "However, the mechanism of IL-5 in alleviating sepsis-induced ALI has not yet been confirmed." (PMID 34057015, 2021). "The negative interactions for the sepsis group were between CCL5 and CXCL9, CCL5 and IL-5, and IL2R and IL-17A." (PMID 35811678, 2022). "However, there are still no relevant studies on whether IL-5 can alleviate sepsis-induced ALI." (PMID 34057015, 2021). "Furthermore, IL-5 has been demonstrated to serve a protective role, independent of eosinophils, in experimental polymicrobial sepsis, suggesting that IL-5 may act on other lung cell targets to promote restoration of pulmonary structure and function following IAV infection." (PMID 24068930, 2013).
dermatitis (31 papers, 2012 to 2025). An inflammatory process affecting the skin. "FC alleviated AD apparent symptoms, such as dermatitis score, transepidermal water loss, epidermal thickness, and mast cell infiltration upon declining pro-inflammatory cytokines and mediators, IL-6, IL-5, IL-13, TSLP, and TNF-α." (PMID 37689763, 2023). "Strikingly, skin inflammation occurs independently of adaptive immunity and is associated with cutaneous expansion of IL-5–producing type 2 innate lymphoid cells." (PMID 26299987, 2016). "We delve into the potential connection between IL-5 and its role in skin inflammation, i.e., prolongation of eosinophil survival time and induction of eosinophil chemotaxis as a result of increased IL-5 expression." (PMID 39062104, 2024). "We have previously reported an increase in circulating IL-5 and IL-5RA mRNA in canines with dermatitis when compared with controls." (PMID 38590952, 2024). "Remarkably, germ-free mice responded highly in key parameters, such as total dermatitis score, ear thickness, TNFα, IL-4, and IL-5." (PMID 28290517, 2017). "Previously, a study demonstrated, by using quantitative RT-PCR, that activated skin ST2+ ILC2s produced more IL-5, leading to eosinophil influx and development of spontaneous dermatitis." (PMID 26299987, 2016). "In the atopy-like dermatitis mouse model, the expression of Th2 cytokines such as IL-4, IL-5, and IL-10 in the lymph nodes of TMA-treated mice was found to be elevated, and BVA largely abrogated TMA-induced production of Th2 cytokines." (PMID 26825274, 2016). "On the other hand, administration of anti-IL-5 effectively depletes eosinophils and mildly increases the severity of epidermal thickness in Sharpincpdm skin, providing some evidence that eosinophils limit dermatitis severity in this model." (PMID 38156288, 2024). "The mediators involved in Th2 reactions include IL-4, IL-5, IL-13, IL-33, and IgE, in which IL-4 triggers dermatitis, similar to its effect in AD by inhibiting the production of IFN-gamma, thereby inducing an immune imbalance and increasing the synthesis of IgE." (PMID 36077570, 2022). "IL-5 and granulocyte-macrophage colony-stimulating factor (GM-CSF) secreted by Th2 cells and mast cells help activate eosinophils, and activated eosinophils, in turn, can produce a variety of proinflammatory molecules to maintain skin inflammation." (PMID 36159556, 2022). "Moreover, IL-33 produced by epidermal keratinocytes can induce ILC2 production from skin tissues and lymph nodes, which further stimulates IL-5 release and induces the occurrence of AD-like dermatitis." (PMID 34925005, 2021). "Interestingly, GMP administration before AD-induction decreased in 83.56, 96.5, and 88.38% the expression of IL-4, IL-5, and IL-13 in dermatitis skin." (PMID 28265582, 2017). "To address the question whether GMP administration might modulate this Th2 inflammatory response in dermatitis, we examined mRNA changes of IL-4, IL-5, and IL-13 by qRT-PCR in injured skin tissue." (PMID 28265582, 2017). "Our results indicated that 7,8,4′-THIF, a metabolite of the soy isoflavone daidzin, suppresses the development of DNCB-induced dermatitis in NC/Nga mice, probably by down-regulating various Th2- (TARC, IL-4, IL-5, and IL-13) and Th1-associated factors (IL-12 and IFN-γ)." (PMID 25170825, 2014). "Depletion of IL5 following treatment with neutralizing anti-IL5 antibodies or crosses with IL5-deficient mice decreased the number of eosinophils, but did not ameliorate the dermatitis, suggesting a limited role for eosinophils in disease development." (PMID 24465642, 2014). "Neutralization of IL5 by antibody treatment or crosses with IL5-deficient mice reduced the number of circulating and cutaneous eosinophils, but failed to reduce the onset and severity of the dermatitis." (PMID 22348129, 2012).
dermatitis (continued). "Moreover, IL-5 extends eosinophil survival time, and what is significant for the clinical observations of patients is that it leads to the initiation and formation of skin inflammation." (PMID 39062104, 2024). "Previous work showed that this dermatitis was not affected by depletion of IL5 and loss of eosinophils, but the inflammation could be prevented by systemic administration of IL12." (PMID 24465642, 2014). "Oral administration or topical treatment of Pentaherbs formula could ameliorate inflammation of oxazolone-mediated dermatitis mice by reducing epidermis thickening, eosinophils and mast cells infiltration and the release of pro-inflammatory cytokine IL-12 (p70) and eosinophil activator IL-5." (PMID 27104513, 2016). "In some mammalian species, prolonged exposure to OVA may lead to the development of dermatitis and infiltration of CD3+ T cells, eosinophils, and neutrophils, as well as increased mRNA levels of interleukin IL-4, IL-5, and IFN-γ." (PMID 35433509, 2022). "The levels of IL-5, IP-10, and soluble FAS-L were significantly increased in the sera of patients with dermatitis, at 7 to 30 days after the initiation of treatment, but not in subjects without dermatitis or uninfected subjects." (PMID 35938810, 2022). "Serum levels of interleukin- 5 (IL-5), soluble Fas cell surface death receptor ligand (FAS-L), and interferon γ-induced protein (IP-10) significantly increased at 7 to 30 days posttreatment with benznidazole and decreased thereafter in subjects with dermatitis but not in those without dermatitis." (PMID 35938810, 2022). "Moreover, the total Dermatitis & Pruritus score was significantly reduced upon mIL‐5‐Qβ mice (mIL‐5‐VLP + OVA) when compared to control vaccination (VLP + OVA), whereas clinical signs were absent throughout the whole observation period for anti‐IL‐5 vaccinated mice." (PMID 40838325, 2025).
pulmonary fibrosis (28 papers, 2013 to 2025). Chronic progressive interstitial lung disorder characterized by the replacement of the lung tissue by connective tissue, leading to progressive dyspnea, respiratory failure, or right heart failure. "Although the direct involvement of IL‐5 in pulmonary fibrosis remains to be fully elucidated, its association with fibrotic mechanisms has become increasingly plausible." (PMID 40641495, 2025). "Further, it was shown that anti-IL-5 antibody caused a significant reduction in lung eosinophils and fibrosis in a bleomycin-induced pulmonary fibrosis mouse model." (PMID 37063828, 2023). "Inducible NOS also contributes to the development of pulmonary fibrosis and underlies the response to a number of pro-fibrotic cytokines, including IL-5 and IL-13." (PMID 24641440, 2014). "Previous studies have confirmed that Th2 cytokines play a leading role in pulmonary fibrosis, and its pathogenesis is related to the secretion of IL-4, IL-5 and IL-13." (PMID 39346776, 2024). "CD103high Tregs can constrain lung fibrosis induced by CD103low tissue-resident pathogenic CD4+ T cells with higher production of effector cytokines, such as IL-4, IL-5, IL-13, IL-17A, and IFN-γ." (PMID 34488453, 2021). "Another study using IL-6 gene silencing showed that, in induced lung fibrosis, IL-6 played an important role in the regulation of the expression of Th2 cytokines (IL-4 and IL-5)." (PMID 34941770, 2021). "T-helper (Th) 1 secretes IFN-γ to reduce pulmonary fibrosis, whereas Th2 cytokines IL-4, IL-5, and IL-13 stimulate fibroblast proliferation, collagen production, and fibroblast activation." (PMID 33647885, 2021). "Summary of key studies supporting a role for IL‐5 in pulmonary fibrosis." (PMID 40641495, 2025). "Obese Nod2−/− mice had higher inflammatory cell infiltration in the bronchial alveolar lavage (BAL) and lungs, pulmonary fibrosis, mucus levels, hypertrophy and hyperplasia of goblet cells, M2 alveolar macrophage infiltration, interleukin-4 (IL-4), IL-5, IL-6, and lower CXCL1 and IL-22." (PMID 39507249, 2024). "In addition to IL-4 and IL-13, it has been observed that IL-5 can also play a role in tissue remodeling in several diseases including pulmonary fibrosis." (PMID 37063828, 2023). "IL-5 recruits and activates eosinophils in bleomycin-induced pulmonary fibrosis." (PMID 36016937, 2022). "IL-5 was reported as a promoter in both liver and pulmonary fibrosis." (PMID 35585990, 2022). "IL-4 and IL-5 were also discovered in the promotion of pulmonary fibrosis." (PMID 35910226, 2022). "While IFN-γ is known to inhibit fibrosis, IL-5 may promote pulmonary fibrosis by its effect on recruiting eosinophils and the subsequent production of TGF-β1, PDGF, and IL-13." (PMID 25944985, 2015). "Patients with pulmonary fibrosis from chronic hypersensitivity pneumonitis exhibit a predominantly Th2 pattern within the interstitial compartment of their lungs characterized by IL-4 and IL-5 activity." (PMID 25944985, 2015). "They suggested a novel mechanism via which TNF-α could mediate pulmonary fibrosis through induction of IL-5-mediated eosinophil recruitment and fibrogenic cytokine production." (PMID 23997916, 2013). "Therefore, we next sought to determine whether IL-5, IL-13, and AREG produced by ILC2s were altered in Hps1−/−-associated lung fibrosis." (PMID 39405112, 2024). "JTE-013 was found to regulate the physiological processes of pulmonary fibrosis and reduce BLM-induced inflammatory pulmonary fibrosis, as evidenced by the results of H&E and Masson staining, and, the expression changes of IL-4, IL-5, IFN-γ, and TNF-α in BALF." (PMID 37895915, 2023). "DHP mainly regulated pulmonary fibrosis-related inflammatory genes and signaling pathways, such as IL1β, IL4, IL5, IL6, TGFβ1, and TNFα." (PMID 31105564, 2019). "By contrast, mIL‐33 may potentiate lung fibrosis by recruiting ST2L+M2‐macrophages and ST2L+ILC2s to enlarge Th2 cytokine milieu by excessive production of IL‐4, IL‐5, and IL‐13." (PMID 36082495, 2022).
pulmonary fibrosis (continued). "In contrast, anti-IL-5 therapy in asthmatic patients is reported to inhibit lung fibrosis without affecting the lung function." (PMID 36016937, 2022). "Although IL-13 contributes to pulmonary fibrosis, lung tissue levels of pro-allergic cytokines such as IL-4 and IL-13 were very low in all groups (<0.5 pg/mg), and IL-5 did not have consistent time- or concentration-dependent responses (data not shown)." (PMID 27083413, 2016).
schistosomiasis (28 papers, 2007 to 2025). An infectious disease caused by parasitic trematodes of the genus Schistosoma that colonize human blood vessels and release eggs that can cause granulomatous reactions leading to acute (swimmer's itch or acute schistosomiasis syndrome) or chronic disease. "The chromosome 5q31–q33 Th2 cluster gene, which regulates the synthesis of interleukin 13, interleukin 4, and interleukin 5, is primarily linked to an increased risk of developing schistosomiasis." (PMID 41179539, 2025). "Since Th2 cytokines such as IL-4, IL-5, and IL-13 are implicated during schistosomiasis, it is worthy to evaluate such interleukins during the coinfection with human African trypanosomiasis." (PMID 37954132, 2023). "Specifically, TH2-associated cytokines IL-4, IL-5, IL-10, and IL-13 from splenic cell preparations appeared elevated in offspring exposed to treated maternal schistosomiasis." (PMID 35833137, 2022). "According to studies, parasite antigens are sensitized in neonates of women who have helminth illnesses such schistosomiasis and filariasis, which are characterized by the production of IL‐4, IL‐5, IgE, and IFN‐ γ." (PMID 39560407, 2024). "Schistosomiasis is characterized by a robust Th2 (T-helper 2) immune response, marked by the production of cytokines such as IL-4, IL-5, and IL-13." (PMID 39452777, 2024). "The genes with the largest literature were the Th2 cytokine genes originally identified by Marquet in SM1 (IL3, IL4, IL5, IL9, and IL13), that each had between 17 and 511 publications associated with schistosomiasis." (PMID 33659002, 2021). "The cytokine levels of TNF-α, IFN-γ, IL-6, IL-4, IL-5, IL-10, IL-13, and IL-17A in the sera of acute phase schistosomiasis were all significantly increased in the IUT and VEH groups compared with the UI group." (PMID 30258438, 2018). "The schistosomiasis group’s median IL-5 levels in response to TT stimulation were higher than uninfected controls at 6 weeks and 8 months following boost." (PMID 27926921, 2016). "Median IL-5 levels were somewhat higher in the schistosomiasis group as compared to the uninfected controls at 6 weeks after vaccination, and significantly higher 8 months after immunization (p < 0.03)." (PMID 27926921, 2016). "In examining other immune indicators and responses we noted that whole blood cultures from those individuals with schistosomiasis produced similar levels of IL-5, IFN-γ and IL-10 as compared to our uninfected controls after stimulation with HbSAg." (PMID 27926921, 2016). "Specific cytokines, in particular IL-2, IL-4, IL-5, IL-10, and IFN-ɤ have been implicated in regulation of granulomatous response on schistosomiasis." (PMID 27378927, 2016). "Field studies in schistosomiasis and filariasis as well as mechanistic experimental studies have reported dissociation in IL-4 and IL-5 production and effector functions." (PMID 21039611, 2010). "For example, both Th1 and Th2 responsiveness appear compromised in schistosomiasis patients, and within the Th2 compartment, IL-5 responses are suppressed while IL-4 production is relatively intact." (PMID 21039611, 2010). "Taken together these results support the proposition that in schistosomiasis at least, IL-10 is acting as a regulatory cytokine which inhibits a protective IL-5 dependent response." (PMID 18045464, 2007). "However, Th2 responses were not thoroughly investigated in this paper, with only one Th2 cytokine (IL-5) assessed, detectable in PBMCs from acute schistosomiasis patients stimulated with schistosome egg antigen (SEA) or schistosome worm antigen (SWA)." (PMID 33953712, 2021). "The dependence on SWA-IgE, a response that increases with age in populations living in schistosomiasis endemic areas, may explain why the peak boost in IL-5 occurred in a slightly older age-group than the peak in infection intensities." (PMID 23556029, 2013).